CLOCK (clock circadian regulator)
Diseases named in the same sentence as CLOCK in open-access papers (continued):
Sharing a sentence is not in itself a finding about the gene and the disease.
diabetes (29 papers, 2010 to 2025). "Night exercise is better than morning exercise in relieving the change in the CLOCK protein level caused by diabetes." (PMID 36012573, 2022). "CLOCK appears to be crucial in glucose homeostasis as well, as both whole body and conditional disruptions of CLOCK caused hypoinsulinaemia hence diabetes mellitus in rodents." (PMID 28108951, 2017). "Two studies analyzed the gene-nutrient interaction between several CLOCK gene variants and diabetes-related traits." (PMID 25421534, 2014). "Moreover, consistent with the expression of CLOCK, night exercise had an advantage over morning exercise in relieving apoptosis caused by diabetes (p < 0.05)." (PMID 36012573, 2022). "At the molecular level, tissue-specific disruption of any clock genes (i.e., CLOCK and BMAL1) regulating circadian rhythm accelerates the development of diabetes through pancreatic beta-cell loss and dysfunction." (PMID 38393018, 2024). "A recent study has indicated the decay of circadian genes (PER, TIM, CLOCK) oscillation with elevated ROS levels in diabetes." (PMID 37215098, 2023). "In contrast, type 2 diabetes mellitus (T2DM) increased the expression of CLOCK and impaired the mitochondrial quality (mitochondrial networks, OPA1, Fis1, and mitophagy), as well as induced apoptosis." (PMID 36012573, 2022). "Disruption of CLOCK and BMAL1 was previously shown cause to hypoinsulinaemia and diabetes in mice, and changes in the synchronization of the beta cells, resulting in loss of pulsatile or first phase insulin secretion, are predictive for both T1D and T2D." (PMID 36589856, 2022). "Disruption of CLOCK and BMAL1 has also been associated with obesity, hyperinsulinemia, and diabetes." (PMID 31847894, 2019). "Deregulation of the clock components CLOCK and BMAL1 have been suggested to cause serious metabolic disorders resulting in serious disorders, such as for example diabetes mellitus and decreased insulin synthesis." (PMID 31151182, 2019). "The carriers of the minor allele (G) in this CLOCK variant showed a lower weight, 31% decreased diabetes risk, and 46% lower risk of hypertension than non-carriers." (PMID 36768893, 2023). "We speculated that the varying effect of diabetes on CLOCK and BMAL1 was due to the heterogeneity of histone modifications." (PMID 36012573, 2022). "Similarly, our results showed that diabetes significantly increased the expression of CLOCK in liver (p < 0.01)." (PMID 36012573, 2022). "The ability of insulin to restore circadian rhythm through BMAL1 and CLOCK genes may facilitate re-epithelialization, as these rhythms may be disturbed in diabetes." (PMID 32194500, 2020). "In addition, diabetes and exercise may selectively or characteristically affect the heterodimer of CLOCK and BMAL1." (PMID 36012573, 2022). "In pancreatic islet tissues, mutants of the circadian gene CLOCK and the protein BMAL1 show significantly impaired glucose tolerance, decreased insulin secretion, and pancreatic β-cell defects, leading to the onset of diabetes." (PMID 40115347, 2025). "Pancreatic β-cells express the molecular clock proteins controlling circadian rhythm of insulin secretion and impairment of some member of the clock genes such as circadian locomotor output cycles kaput (CLOCK) and brain and muscle ARNT-like 1 (BMAL1), leading to hypoinsulinemia and diabetes." (PMID 24672804, 2014). "For instance, CLOCK and BMAL1 disruption leads to alterations in the expression of beta-cell genes involved in growth, survival and synaptic vesicle assembly, which can trigger the onset of diabetes." (PMID 23936124, 2013).
glioblastoma (28 papers, 2020 to 2026). The most malignant astrocytic tumor (WHO grade IV). "Glioblastoma (GBM) is a highly aggressive brain tumor characterized by extensive crosstalk between glioblastoma stem cells (GSCs) and immunosuppressive microglia, with our previous work identifying CLOCK and TFPI2 as key regulators of this interaction." (PMID 41842961, 2026). "The master genes BMAL1 and CLOCK are both essential for the survival of glioblastoma CSCs, so the researchers developed a Cry activator, SHP1705, which helps inhibit BMAL1 and CLOCK transcriptional activity." (PMID 40869256, 2025). "For example, reducing the expression of BMAL1 or CLOCK in glioblastoma stem cells (GSCs) can induce cell cycle arrest and trigger apoptosis." (PMID 40046513, 2025). "There has also been a study that demonstrates the inhibitory effect of CLOCK on glioblastoma through the OLFML3-HIF1α-LGMN pathway." (PMID 38703241, 2024). "Recent one study has revealed that CLOCK exerts a tumor-promoting effect on glioblastoma progression via the POSTN-TBK1 signaling pathway." (PMID 38703241, 2024). "In glioblastoma multiforme, CLOCK expression is correlated with higher microglial presence and reduced activation of CD8+ T cells in a non-diurnal manner." (PMID 39413708, 2024). "CLOCK also participates in regulating the microglial content of glioblastoma stem cells (GSC) in glioblastoma (GBM) through transcriptional regulation of chemokines." (PMID 38678017, 2024). "In glioblastoma tissue and in cell culture, CLOCK was found to positively regulate glioblastoma migration by upregulating activity of transcription factor nuclear factor-κB (NF-κB), thus promoting mesenchymal differentiation." (PMID 38173841, 2023). "Downregulating BMAL1 or CLOCK triggers reduced cell proliferation rate in the glioblastoma stem cells (GSCs), hepatocellular carcinoma (HCC) cells, and leukemia stem cells, featured by a symbolic cellular response of cell cycle dysregulation." (PMID 36937362, 2023). "Similar to these results, a subsequent GBM model study showed that downregulation of CLOCK or BMAL1 in glioblastoma stem cells (GSCs) induced cell-cycle arrest and apoptosis." (PMID 36430659, 2022). "We recently reported that the genome-wide BMAL1::CLOCK occupancy in glioblastoma stem cells was more expanded as compared with normal neural stem cells." (PMID 34732735, 2021). "Another study found that the circadian clock gene CLOCK promotes tumor cell metabolism and microglia infiltration into the tumor microenvironment, flagging CLOCK as a novel therapeutic target for Glioblastoma." (PMID 32681792, 2020). "Notably, simultaneous targeting of LOX and CLOCK pathways effectively interrupted macrophage and microglial infiltration in PTEN-deficient glioblastoma, markedly enhancing anti-tumor immune responses." (PMID 40076738, 2025). "Likewise, the upregulation of chemoattractant olfactomedin-like 3 (OLFML3) by BMAL1 and CLOCK facilitates the migration of immunosuppressive microglia into the glioblastoma TME." (PMID 39413708, 2024). "The CLOCK gene is amplified in ~ 5–9% of glioblastoma patients." (PMID 32631383, 2020). "For example, BMAL1::CLOCK recruits immune-suppressive microglia cells to the TME of glioblastoma (GBM) via transcriptional activation of the OLFML3 gene." (PMID 36937362, 2023). "LOX influences macrophage infiltration through NF-κB-PATZ1 signaling, while CLOCK modulates microglial recruitment via the OLFML3 axis, both contributing to immune suppression in glioblastoma." (PMID 40076738, 2025). "The core circadian regulator CLOCK/BMAL1 complex is reported to sustain cancer stem-like traits and immunosuppression features of glioblastoma." (PMID 39054537, 2024). "Inhibiting any part of this CLOCK–OLFML3–HIF1α–LGMN axis results in reduced immunosuppressive microglial recruitment and prolonged survival in glioblastoma murine models." (PMID 38173841, 2023).
glioblastoma (continued). "Recently, circadian markers such as CLOCK and BMAL1 have been tied to immune suppression in glioblastomas by increasing microglia infiltration." (PMID 38173841, 2023). "Expression of the circadian gene CLOCK specifically demonstrates a positive correlation with LMGN and OLFML3 in glioblastoma." (PMID 38173841, 2023). "A notable exception is in glioblastoma stem cells (GSCs), where GSCs with amplified MYC maintained oscillation and actually relied on CLOCK and BMAL1 to maintain stemness." (PMID 37639465, 2023). "Targeting the CLOCK–OLFML3–HIF1α–LGMN–CD162 axis reduces PD-L1 expression and augments anti-PD1 therapy in glioblastoma mice, overall highlighting the therapeutic potential of this pathway." (PMID 38173841, 2023). "In solid tumors, glioblastoma stem cells (GSCs) dependent on core circadian clock transcription factors, BMAL1 and CLOCK, for their cell growth, and targeting core clock factors in GSCs suppresses their tumor growth." (PMID 33816508, 2021). "Normal neural stem cell growth was unaffected by CLOCK and BMAL1 knockdown, indicating that glioblastoma cells are unique in relying on these circadian transcription factors for maximum cell growth." (PMID 32631383, 2020). "CLOCK and BMAL1 knockdown decreased glioblastoma proliferation through cell-cycle arrest and apoptosis." (PMID 32631383, 2020). "Additionally, CLOCK and BMAL1 in GSCs play a role in immunosuppression in glioblastoma." (PMID 40046513, 2025).
bipolar disorder (21 papers, 2009 to 2025). A disorder of the brain that causes unusual shifts in mood, energy, activity levels and the ability to carry out day-to-day tasks. "This is revealing, as abnormalities in circadian rhythms are considered to play a potential underlying role in bipolar disorder, as many genes associated with bipolar disorder including CLOCK, PER3 and BMAL1 are regulated in a circadian manner." (PMID 37730845, 2023). "In another study in bipolar disorder patients, a significant interaction between CLOCK variants and early stress exposure on hopelessness and suicide in BP patients was reported." (PMID 34512413, 2021). "Meanwhile, polymorphisms rs11932595 and rs3805148 of the CLOCK gene were also found to be associated with sleep type and sleep disorder in patients with single or bipolar depression." (PMID 32908891, 2020). "For our investigation we selected rs10462028 of CLOCK, which has been used as a tagSNP of CLOCK in a previous study showing its association with bipolar disorder —a comorbid disease of migraine with overlapping genetic factors." (PMID 32038187, 2019). "While further studies are required, so far, variations of Per3 have been associated with age of onset of mood disorders, response to treatment and circadian mood variations and Per 3, Bmal1, CLOCK, Nr1d1 and Nr1f2 have all been linked to bipolar disorder." (PMID 23521808, 2013). "The TDT association of 6 CLOCK SNPs with bipolar disorder was intriguing, and appeared consistent with the claim that a CLOCK mutation in mice produces a mouse analog of mania." (PMID 19166596, 2009). "Similarly, research analyzing single-nucleotide polymorphisms (SNPs) has associated the CLOCK gene with bipolar disorders." (PMID 39584972, 2024). "In addition, they found increased seasonal variations of mood and behavior among individuals carrying a CLOCK polymorphism previously implicated in bipolar disorder." (PMID 30190706, 2018). "Specifically, on the one hand, CLOCK and VIP variants appear to be selectively associated with bipolar disorders." (PMID 36833279, 2023). "The interaction between CLOCK gene rsll932595 and ARNTL gene rsl1824092 was associated with sleep disorders in patients with bipolar disorder." (PMID 32908891, 2020). "The CLOCK 3111 T/C SNP, located in the 3′-UTR region of the CLOCK gene, associates with a higher recurrence rate of major depressive episodes in bipolar depression patients, and with greater insomnia and decreased need for sleep in bipolar patients." (PMID 24905098, 2014). "Circadian gene polymorphisms in CLOCK and VIP, and NR1D1, ARNTL and PER3 have previously been associated to human bipolar disorder." (PMID 20856823, 2010). "The studied clock gene CLOCK (Circadian Locomotor Output Cycles Kaput) and its binding partner BMAL1 (also known as Aryl hydrocarbon receptor nuclear translocator-like protein 1 or ARNTL1) were associated with bipolar disorder phenomena in genetic studies." (PMID 28588455, 2017). "Studies of clinical populations suggest that variation in genes implicated in the circadian clock including CLOCK, PER3, BMAL1, TIMELESS, NPAS2, NR1D1, RORB and GSK3β may contribute to the genetic component of bipolar disorder." (PMID 22719873, 2012). "Perhaps the most convincing evidence so far has emerged from bipolar disorder with some evidence of association with period homolog 3 (Drosophila) (PER3), ARNTL, basic helix-loop-helix family, member e40 (BHLHE40), casein kinase 1, epsilon (CSNK1E), and CLOCK." (PMID 20174623, 2010). "In particular, Benach and colleagues investigated the possible link among polymorphisms of CLOCK, ARNTL, TIMELESS, and PER3 genes (complex analysis of single polymorphisms and haplotypes–SNP interactions) and the comorbidity of alcohol abuse (AAD) in bipolar disorder patients." (PMID 35893041, 2022).
sleep disorder (20 papers, 2009 to 2025). A change from the patient's baseline sleeping pattern, in the hours slept and/or an alteration/dysfunction in the stages of sleep. "CLOCK gene polymorphisms are closely associated with circadian preference, sleep duration, and sleep disorders, and affect the efficacy of caffeine citrate in AOP treatment." (PMID 39108697, 2024). "For example, etiological studies reported that the risk of developing insomnia was connected to the CLOCK gene associated with sleep disorders and poor sleep quality due to circadian disruption." (PMID 37242182, 2023). "The CLOCK gene was significantly associated with sleep disorders and poor sleep quality due to circadian disruption." (PMID 37242182, 2023). "The interaction between mental health and CLOCK gene polymorphisms was found to be a risk factor for sleep disorders." (PMID 32908891, 2020). "The CLOCK gene mutation leads to the development of hyperphagia, hyperlipidemia, hyperinsulinemic hyperglycemia and sleep disorders." (PMID 32344535, 2020). "The polymorphism of the CLOCK 3111T/C gene locus was associated with sleep disorders in depressed people: people with TC and CC alleles were more likely to have difficulty falling asleep, early wakening, and poor sleep maintenance." (PMID 32908891, 2020). "In humans, the CLOCK gene has already been associated with the evening chronotype as well as with some circadian and sleep disorders, such as delayed sleep phase syndrome." (PMID 30696097, 2019). "The CLOCK 3111T/C variant can be an independent risk factor for motor fluctuation and sleep disorder in Parkinson's disease." (PMID 29535854, 2018). "This showed that a polymorphism of CLOCK 3111T/C can be an independent risk factor for the sleep disorder in Parkinson's disease (OR = 1.130, 95% CI = 1.007–1.2689, P=0.037)." (PMID 29535854, 2018). "CLOCK 3111T/C variant can be an independent risk factor for motor fluctuation and sleep disorder in Parkinson's disease in Chinese population." (PMID 29535854, 2018). "In conclusion, our results showed that the 3111T/C variant of CLOCK gene was closely related to the occurrence of motor fluctuation and sleep disorders in a northeastern Chinese population." (PMID 29535854, 2018). "This suggested that the rs1801260 and rs6850524 loci of CLOCK gene might be associated with sleep disorders." (PMID 32908891, 2020). "Therefore, we further confirmed that the polymorphism of CLOCK 3111T/C can be an independent risk factor for sleep disorders in PD." (PMID 29535854, 2018). "The logistic regression results suggested that CLOCK gene rs1801260 (TC) and positive psychological symptoms were influential factors for sleep disorders, and the interaction of positive psychological symptoms∗rs1801260 (TT) was a risk factor for sleep disorders (OR = 10.833, 95% CI: 2.987–39.288)." (PMID 32908891, 2020). "Sleep disorders disrupt the expression of circadian rhythm-related genes (such as CLOCK and BMAL1) via epigenetic mechanisms, further worsening neuronal damage." (PMID 40264463, 2025). "Thus, the CLOCK 3111T/C polymorphism could be an independent risk factor for sleep disorders in PD." (PMID 38201415, 2024). "It is suggested that the TC genotype at rs1801260 of the CLOCK gene and positive psychological symptoms are factors influencing sleep disorder." (PMID 32908891, 2020). "The sleep disorders used 1 : 1 matching, finally providing a sample with 60 cases and 60 controls for measurement of the CLOCK gene (rs1801260, rs6850524), to analyze the effect of the interaction between mental health and the CLOCK gene on sleep." (PMID 32908891, 2020). "In the model, rs1801260 (TT) of the CLOCK gene was used as the reference group, and rs1801260 (TC) was a protective factor for sleep disorders (OR = 0.434, 95% CI: 0.240–0.785)." (PMID 32908891, 2020). "Animal experiments concerning the CLOCK gene provide putative mechanistic links between circadian/sleep disorder and ADHD pathophysiology." (PMID 30696097, 2019).
sleep disorder (continued). "Also, it was determined that the CLOCK rs1801260 gene TC genotype was protective compared to the TT genotype for sleep disorder (OR = 0:434, 95% CI: 0.240–0.785) in multiple logistic regression analysis." (PMID 39744380, 2024). "Circadian rhythm genes mainly altered in malignant nodules, and sleep disorders may be involved in the occurrence of elderly thyroid malignancy through the high expressions of CLOCK and BMAL1, and low expression of CRY2." (PMID 34211057, 2021). "The rs10462028 and rs11932595 of the CLOCK gene, the rs934945 of the PER2 gene, and the distribution of genotypes and allele frequencies of each genotype, as well as allele frequency, were significantly different in the sleep-disordered group and the normal-sleep group (both p < 0.001)." (PMID 40951374, 2025). "Studies have shown that sleep disorders may involve genetic factors, including CLOCK genes." (PMID 32908891, 2020). "Previous studies have primarily focused on CLOCK and PER2 in sleep disorders, but RORA’s role remains underexplored, particularly in mental worker populations." (PMID 40951374, 2025). "Correlation study of CLOCK, PER2, and RORA genes with sleep disorders." (PMID 40951374, 2025). "It is important to highlight that the CLOCK gene was neither associated with ADHD nor with chronotype, sleep duration, or sleep disorders in the most comprehensive and recent genome-wide association studies (GWAS)." (PMID 30696097, 2019). "In a study conducted on surgical nurses with and without sleep disorders, PSQI total scores and subcomponents (excluding hypnotic drugs) of individuals with the CLOCK rs1801260 gene TT genotype were higher than in individuals with the CC genotype." (PMID 39744380, 2024). "Similarly, though various associations with several bipolar phenotypes such as recurrence rates and sleep disturbances have been reported with rs1801260, the T3111C SNP in the 3'UTR region of CLOCK, it is possible that rs1801260 is not the most functional polymorphism in linkage disequilibrium." (PMID 19166596, 2009).